FUT2 (fucosyltransferase 2 (H blood group))
Diseases named in the same sentence as FUT2 in open-access papers (continued):
Sharing a sentence is not in itself a finding about the gene and the disease.
Hypertension (3 papers, 2018 to 2023). The presence of chronic increased pressure in the systemic arterial system. "Exploration of phenome-wide associations for fucosyltransferase 2 (FUT2) p.Trp154Ter in the UK Biobank showed significant associations with dyslipidemia, hypertension and cholelithiasis." (PMID 37277652, 2023). "We identified 87,176 predicted homozygous KOs for FUT2 caused by a common PTV rs601338 with MAF 49.1% and identified non-additive risk associations between FUT2 KO status and eight phenotypes including hypertension and mumps." (PMID 29691392, 2018).
liver cancer (3 papers, 2016 to 2024). An epithelial or non-epithelial malignant neoplasm that arises from the liver. "Additionally, in liver cancer, Fut2 was reported to increase levels of Globo H and enhance cancer cell proliferation." (PMID 36739428, 2023).
melanoma (3 papers, 2018 to 2023). A malignant, usually aggressive tumor composed of atypical, neoplastic melanocytes. "For instance, a lectin microarray of melanoma identified FUT2 as an anti-metastatic factor, and silencing FUT2 promoted the invasion of melanoma cells." (PMID 36973740, 2023). "We examined the changes of FUT1and FUT2 expression levels during melanoma progression in five previously published datasets (GSE8401, GSE46517, GSE 7553, GSE15605 and GSE3189)." (PMID 29924834, 2018). "It is interesting to note that the expression of FUT1 and FUT2, the two α-1,2 fucosyltransferases, are suppressed during melanoma progression, and the levels of α-1,2 fucosylation are inversely correlated with the survival of melanoma patients." (PMID 29924834, 2018). "Fucosyltransferase 1 and 2 (FUT1 and FUT2) are the fucosyltransferases responsible for the transfer of L-fucose to glycans via α-1,2 linkages and has been shown to be involved in inhibition of melanoma cell migration and adhesion." (PMID 29924834, 2018). "In contrast, there was no clear correlation between FUT2 mRNA levels and melanoma progression in these datasets." (PMID 29924834, 2018). "Although in some datasets there appeared to be down-regulation of FUT2 mRNA in metastatic melanoma when compared to primary melanonma (GSE46517,GSE15605), in other datasets there was either no changes or increases in FUT2 expression with melanoma progression (GSE8401, GSE7553, GSE3189)." (PMID 29924834, 2018).
metabolic syndrome (3 papers, 2020 to 2023). A cluster of metabolic risk factors for CARDIOVASCULAR DISEASES and TYPE 2 DIABETES MELLITUS. "In conclusion, we examined 18 previously reported SNPs of metabolic syndrome in a Chinese Han population and found that 7 SNPs located in HLA, FUT2, and LNPEP were associated with PsV in Chinese Han." (PMID 34589554, 2021). "FUT2 has relationship with dyslipidemia due to the regulation of glycosphingolipid synthesis." (PMID 34589554, 2021).
mumps (3 papers, 2017 to 2018). "FUT2 (rs516316, P = 9.63 × 10−72, OR = 1.25) and ST3GAL4 (rs3862630, P = 1.21 × 10−8, OR = 1.13) also have highly significant associations with mumps." (PMID 28928442, 2017).
Peptic ulcer (3 papers, 2021 to 2023). The term peptic ulcer refers to acid peptic injury of the digestive tract, resulting in mucosal break reaching the submucosa. "In the UK Biobank, ABO, CDX2, CCKBRMUC1, MUC6, FUT2, PSCA, and GAST genes have been identified and found to be associated with peptic ulcer disease." (PMID 36678166, 2023).
Respiratory Infections (3 papers, 2020 to 2023). "The most significant signal implicated the gene FUT2 which has been widely studied for its role in blood group antigen expression and association with gastric and respiratory infection." (PMID 37263751, 2023). "A potential role of FUT2 for respiratory infections is supported by a recent candidate–gene study reporting association between the FUT2 rs601338 G allele and a diagnosis of lower respiratory tract illnesses at 12–24 months of age40." (PMID 33328473, 2020).
adenoma (2 papers, 2023 to 2025). A neoplasm arising from the epithelium. "The researchers also found that individuals with the rs281377 TT genotype had a greater risk of adenoma when stratified by FUT2 genetic polymorphisms." (PMID 39744516, 2025). "They found that long‐term or recurrent antibiotic use increased the risk of early‐onset CRC and adenomas, with a stronger effect in people with a particular variant of the gut microbiota regulatory gene, Fucosyltransferase 2 (FUT2)." (PMID 37504220, 2023). "Herein, we used data from the UK Biobank (a) to investigate the associations of LRAU during early life with EOCRC risk overall and according to genetic factors, and (b) to test whether the association between LRAU and risk of EOCRC as well as adenomas differs by the genetic polymorphisms of FUT2." (PMID 37504220, 2023).
cholelithiasis (2 papers, 2023 to 2025). The presence of crystallized deposits forming in the gallbladder or biliary tree, primarily composed of cholesterol, bilirubin, and bile. "Seven genes, including GCKR, SNX17, ABCG8, MARCH8, FUT2, APOH, and HNF1A, were revealed to be colocalized with the causal signal between sphingomyelin and cholelithiasis." (PMID 40428345, 2025).
colon adenocarcinoma (2 papers, 2014 to 2016). "It was reported that β1, 3- Galactosyltransferase is down-regulated in colon adenocarcinomas and causes CEA express with absence of type 1 chain, but the relation between FUT2 and CEA was still unknown." (PMID 24941225, 2014).
colorectal tumor (2 papers, 2019 to 2023). "The expression of Fut2 and α-1,2-fucosylation was lower in colorectal tumor tissues than in the adjacent normal tissues of AOM/DSS-induced CRC mice." (PMID 36739428, 2023).
E. coli infection (2 papers, 2019 to 2025). "In addition, resistance to F18+ E. coli infection has been associated with multiple genetic loci including FUT1, FUT2, ST3GAL1, and B3GALNT." (PMID 39917050, 2025). "Prof. Cox’s group is currently analysing data to suggest the genetic regulation of FUT2 (a gene closely related to FUT1), might also be controlling blood group A and O blood expression in the pigs small intestine, and thus piglet susceptibility to F18+ E. coli infection." (PMID 30709726, 2019).
gallstones (2 papers, 2018 to 2024). Solid crystalline precipitates in the biliary tract, usually formed in the gallbladder, resulting in the condition of cholelithiasis. "Among the novel gallstone variants, two are in fucosyltransferase genes (FUT2 and FUT6)." (PMID 30504769, 2018). "Three novel gallstone-associated non-coding variants at the LITAF and MAL2 loci and a stop gained variant at the FUT2 locus are correlated with (r2 > 0.8) or represent the strongest cis-eQTLs in their respective regions." (PMID 30504769, 2018). "Six of the novel gallstone associated variants, or highly correlated variants (r2 > 0.8), have been reported to associate with blood cholesterol levels (in HNF4A, HNF1A, FUT2, FADS2, MARCH8, and JMJD1C)." (PMID 30504769, 2018).
lung carcinoma (2 papers, 2017 to 2022). "The results showed that the expression of FUT2 was significantly higher in lung cancer cells (A549, H1299, and H460) than in Beas-2B cells, especially in A549 cells." (PMID 36552800, 2022). "Here, we found that the expression of LC3-II in lung cancer cell lines was correlated with the expression of FUT2." (PMID 36552800, 2022). "The results showed that the expression of LC3-II was higher in lung cancer cells (A549, H1299, and H460) than in Beas-2B cells, which is consistent with the expression of FUT2 in these cell lines." (PMID 36552800, 2022). "However, there are no reports about the pathological role of fucosyltransferase 2 (FUT2) in lung cancer." (PMID 29228607, 2017).
meningioma (2 papers, 2014 to 2024). A generally slow growing tumor attached to the dura mater. "High expression of FUT1, FUT2, FUT3, FUT6, FUT7, and FUT8 in malignant meningioma cell lines—HKBMM and IOMM-Lee—may represent a fucosylation signature of mucin-type O-linked glycosylation in malignant meningiomas." (PMID 38274327, 2024). "We found that the respective expression of FUT2, FUT3, FUT6, and FUT7 was also increased in the malignant meningiomas—HKBMM and IOMM-Lee." (PMID 38274327, 2024). "FUT1, FUT2, FUT3, FUT6, FUT7, and FUT8 were highly increased in malignant meningioma cell lines." (PMID 38274327, 2024).
Stroke (2 papers, 2023). Sudden impairment of blood flow to a part of the brain due to occlusion or rupture of an artery to the brain. "Partitioning the whole genome into LD-independent regions, only one significant region was observed for GSD and stroke (19q13.33, harboring FUT2, a previous-reported locus for GSD and stroke)." (PMID 37705021, 2023). "In contrast, there was no significant change in Fut2 mRNA levels in young males after stroke." (PMID 37910478, 2023).
AIDS (1 paper, 2017). A syndrome resulting from the acquired deficiency of cellular immunity caused by the human immunodeficiency virus (HIV). "The specific SNPs associated with having multiple AIDs were neuropilin 1 (NRP1, rs2666236), RGS1 (rs2816316), CD69 (rs4763879), and FUT2 (601338)." (PMID 29182645, 2017).
alcoholic hepatitis (1 paper, 2025). Acute hepatitis resulting from ingestion of alcohol. "FUT2 protein expression in the colonic epithelial cells of patients with alcohol misuse and alcoholic hepatitis was markedly decreased compared to normal controls." (PMID 40817598, 2025). "One limitation of our study is the absence of genotyping data for the FUT2 variant in patients with alcohol misuse and alcoholic hepatitis." (PMID 40817598, 2025).
atherosclerosis (1 paper, 2015). A disease characterized by the build-up of fatty material and calcium deposition in the arterial wall resulting in partial or complete occlusion of the arterial lumen. "Recently, phosphatidylcholine metabolism, which is related to glycosphingolipid synthesis (FUT2), was implicated in atherosclerosis risk." (PMID 25853426, 2015).
bronchiectasis (1 paper, 2023). Segmental, irreversible dilation of the bronchial tree resulting in the accumulation of secretions which leads to obstruction. "Research has shown that FUT2 polymorphism is closely associated with the prognosis of non-CF bronchiectasis." (PMID 37256139, 2023). "FUT2 genotype influences exacerbation and infection in non-CF bronchiectasis." (PMID 37256139, 2023). "Patients with non-CF bronchiectasis with homozygous secretors of FUT2 had a poorer prognosis compared with those of nonsecretors and heterozygous secretors and exhibited lower lung function, more exacerbation, and a higher frequency of Pseudomonas aeruginosa-dominated infection." (PMID 37256139, 2023). "Therefore, FUT2 and α-1,2-fucosylation may serve as potential therapeutic targets for non-CF bronchiectasis." (PMID 37256139, 2023). "FUT2 genotype in patients with non-CF bronchiectasis may also predict the disease outcomes." (PMID 37256139, 2023).
childhood asthma (1 paper, 2020). "Based on the known biological function of FUT2 for the secretion of A and B antigens on epithelial surfaces, including airway epithelium, we looked for evidence of an association between the ABO locus on chromosome 9 and childhood asthma with severe exacerbations." (PMID 33328473, 2020).
Epileptic encephalopathy (1 paper, 2024). A condition in which epileptiform abnormalities are believed to contribute to the progressive disturbance in cerebral function. "Here, we report an infant with vitamin B12-responsive developmental and epileptic encephalopathy due to a novel mutation in the fucosyltransferase 2 (FUT2) gene responsible for vitamin B12 absorption." (PMID 39350204, 2024). "We report a novel variant in the FUT2 gene associated with vitamin B12-responsive developmental and epileptic encephalopathy and megaloblastic anaemia." (PMID 39350204, 2024). "The whole exome sequencing revealed a homozygous missense variant in exon 2 of the FUT2 gene associated with reduced vitamin B12 absorption and low plasma vitamin B12 levels, confirming the diagnosis of vitamin B12 deficiency related developmental and epileptic encephalopathy." (PMID 39350204, 2024).
gastrointestinal infection (1 paper, 2018). "Interestingly, we observe opposing effects of the FUT2 variant rs601338 on the risk of gallstone disease and susceptibility to gastrointestinal infection." (PMID 30504769, 2018).
glaucoma (1 paper, 2024). Increased pressure in the eyeball due to obstruction of the outflow of aqueous humor. "Understanding the molecular mechanism linking EndoMT and SC could be crucial for deciphering the role of glaucoma-associated genes like FUT2 and CDH5 and their impact on endothelial function." (PMID 38287276, 2024). "Although FUT2 is associated with significant antibody reactivity in the glaucoma patient group, its exact role in the disease’s pathology remains unclear." (PMID 38287276, 2024). "One possible direct connection may be that elevated FUT2 is related to a dysfunction within the Schlemm’s canal, a vascular structure associated with glaucoma." (PMID 38287276, 2024). "Elucidating the relationship between FUT2, CDH5, and endothelial function in the context of glaucoma may provide valuable insights into the disease’s pathology and open new avenues for targeted therapeutic approaches." (PMID 38287276, 2024). "Some of these autoantibodies react with proteins which have previously been associated with glaucoma, such as LOX and TMEM9B, as well as proteins which have little or no previous association with the disease, such as CDH5 and FUT2." (PMID 38287276, 2024).
glioblastoma (1 paper, 2025). The most malignant astrocytic tumor (WHO grade IV). "Many of the identified differentially expressed genes are understudied in glioblastoma; however, several are key regulators of tissue remodeling (MFAP4 and ALX4), mesoderm development (TBX5 and ALX4), and immune modulation (FUT2, C4BPA, MFAP4, and GRM4)." (PMID 41066027, 2025).
malaria (1 paper, 2021). Malaria is a serious and sometimes fatal disease caused by a parasite that commonly infects a certain type of mosquito which feeds on humans. "FUT2 could have evolved neutrally in hominins before the late occurrence of selective pressure, in the same way as for glucose transporters (GLUT 2 and 12) and G6PD2 with malaria." (PMID 34320013, 2021).
metastasis (1 paper, 2014). The spread or migration of cancer cells from one part of the body (where they first appeared) to another. "SNPs associated with the CEA level and regional lymph metastasis, rs1047781 (chr19- FUT2) and rs8176746 (chr9- ABO), were not the independent contributors to disease-free survival." (PMID 24941225, 2014).
mood disorder (1 paper, 2024). A cognitive disorder a disturbance in which the person's mood is hypothesized to be the main underlying feature. "The review highlights the impact of COMT rs4680 on stress response and mood disorders, FUT2 rs602662 and rs601338 on vitamin B12 absorption and cortisol metabolism, and MTHFR rs1801133 and rs1801131 on homocysteine levels and cardiovascular risk." (PMID 39642577, 2024).
mucinous ovarian tumor (1 paper, 2015). "For validation of this particular hypothesis, nine mucinous ovarian tumor samples were selected and subjected to pyrosequencing analysis of FUT2 gene." (PMID 26075384, 2015).
Neonatal sepsis (1 paper, 2022). Systemic inflammatory response to infection in newborn babies. "We constructed a directed acyclic graph of the known associations between FUT2, neonatal sepsis, prematurity, and T1D, and included associations between anti-gentamicin IgG levels and FUT2 and anti-gentamicin IgG levels and T1D (red)." (PMID 36316364, 2022).
oral disease (1 paper, 2012). "We studied the possible association between the 428 G-A in the FUT2 gene and oral disease progression." (PMID 22157667, 2012).
ovarian tumor (1 paper, 2023). "We observed 24 ABH antigen synthesis‐related genes in which five genes (FUT1, FUT2, FUT3, B3GNT3, and B3GNT2) were up‐regulated and three genes (ST3GAL3, ST3GAL4, and B3GALT2) were down‐regulated in ovarian tumor tissue versus adjacent tissues in all samples." (PMID 36415180, 2023).
pancreatitis (1 paper, 2022). Inflammation of the pancreas. "Other genetic factors related to pancreatitis are Calcium Sensing Receptor (CASR), Claudin 2 (CLDN2), Carboxyl Ester Lipase (CEL), Cathepsin B (CTSB), Myosin IXB (MYO9B), Ubiquitin Protein Ligase E3 Component N-Recognin 1 (UBR1), and Fucosyltransferase 2 (FUT2)." (PMID 36434531, 2022).
pneumonia (1 paper, 2023). An acute, acute and chronic, or chronic inflammation focally or diffusely affecting the lung parenchyma, caused by an infection in one or both of the lungs (by bacteria, viruses, fungi, or mycoplasma.). "Specifically, through a univariate regression analysis, we evaluated the association between risk allele carrier status for each genetic variant (OAS1/2/3, DPP9, IFNAR2, LZTFL1, ABO, and FUT2) and the development of clinical complications and of pneumonia." (PMID 36873632, 2023).
Salmonella Infections (1 paper, 2019). Infections with bacteria of the genus SALMONELLA. "Here, we investigated the role of host fucosylation in disease development during Salmonella infection using mice with and without expression of the Fut2 gene (Fut2+/+ and Fut2-/-)." (PMID 31329635, 2019).
schizophrenia (1 paper, 2023). A major psychotic disorder characterized by abnormalities in the perception or expression of reality. "For example, 19q13.33 was particularly colocalized between PUD and schizophrenia not only with the prevalence of Ruminococcaceae species but with the abundance of Bacteroides species, where the index SNV rs681343 (mapped gene: FUT2) was also identified as shared causal variant." (PMID 36753304, 2023). "The index SNVs rs681343 (PLACO P = 1.36 × 10−12 for PUD-schizophrenia) and rs601338 (PLACO P = 5.07 × 10−11 for PUD-ADHD) at 22q13.2 were in high LD (r2 = 0.996) and had almost identical eQTL regulation information (eTable 7 in Supplement 1), regulating the expression of FUT2 (OMIM 182100)." (PMID 36753304, 2023). "Interestingly, the 19q13.33 locus, which was identified as pleiotropic loci for 2 pairs of traits, was only colocalized between PUD and schizophrenia (PP.H4 = 0.8927) rather than PUD and ADHD (PP.H4 = 0.3552), with the same potential shared causal variant rs681343 identified (mapped gene: FUT2)." (PMID 36753304, 2023).
vitamin B12 deficiency (1 paper, 2024). A disease characterized by low serum levels of vitamin B12, either inherited or acquired. "FUT2 mutation is associated with reduced vitamin B12 absorption and low plasma vitamin B12 levels, thus confirming the diagnosis of vitamin B12 deficiency associated with DEE in the index patient." (PMID 39350204, 2024).